KIT (KIT proto-oncogene, receptor tyrosine kinase)
Diseases named in the same sentence as KIT in open-access papers (continued):
Sharing a sentence is not in itself a finding about the gene and the disease.
renal tubular acidosis (1 paper, 2023). A group of genetic disorders of the kidney tubules characterized by the accumulation of metabolically produced acids with elevated plasma chloride, hyperchloremic metabolic acidosis. "The abnormal expression of KIT and its correlated DEGs might be a signal related to kidney failure disease, smoking behaviors, renal tubular acidosis, distal, autosomal recessive, pseudohypoaldosteronism, type II and hyperactive renin-angiotensin system disease." (PMID 37808589, 2023).
right ventricular cardiomyopathies (1 paper, 2021). "Additionally, silencing of c-KIT had a significant effect on the down-regulation of genes of hypertrophic, dilated and arrhythmogenic right ventricular cardiomyopathies." (PMID 33469076, 2021).
salivary duct carcinoma (1 paper, 2024). An aggressive, high grade adenocarcinoma that arises from the salivary glands. "A few studied cases of salivary duct carcinoma (SDC) were positive for CD24 and CD44, while almost all cases were negative for c-KIT." (PMID 39858584, 2024).
schistosomiasis (1 paper, 2023). An infectious disease caused by parasitic trematodes of the genus Schistosoma that colonize human blood vessels and release eggs that can cause granulomatous reactions leading to acute (swimmer's itch or acute schistosomiasis syndrome) or chronic disease. "CD117/KIT expression was seen in 71.7% of cases that correlated significantly with schistosomiasis (P = 0.01)." (PMID 37338655, 2023). "In addition, a positive correlation was detected between schistosomiasis association and the percentage of immunostained cells and intensity score of CD117/KIT with P = 0.027, 0.01, respectively." (PMID 37338655, 2023).
Spitz nevi (1 paper, 2021). "KIT expression was found to be positive in all Spitz nevi, particularly in their junctional component, as we also report for the most part; all six junctional Spitz nevi presented KIT positivity, whereas the dermal one was negative." (PMID 34769348, 2021).
tenosynovial giant cell tumor (1 paper, 2025). A tumor usually arising in the synovium of joints, bursa or tendon sheath. "PLX3397, an orally available inhibitor of CSF-1R and KIT, given daily, has received FDA approval for treatment of tenosynovial giant cell tumor." (PMID 40760255, 2025).
tongue cancer (1 paper, 2025). A malignant neoplasm affecting the tongue. "Red rectangles represent the hit genes involved in the treatment of tongue cancer (TERT, Bcl-2, CDK4/6, CDK2, VEGF, ER, RXR,c-KIT, MET, FGFR, PPAR8, PFFP, MMPs, CDK4, AR, F2, IGFR)." (PMID 39863836, 2025).
urinary bladder small cell carcinomas (1 paper, 2023). "Moreover, a previous study on urinary bladder small cell carcinomas demonstrated CD117/KIT overexpression in 27% of the studied cases." (PMID 37338655, 2023).
Williams Beuren syndrome (1 paper, 2021). "Another candidate is Wbscr25 (Williams Beuren syndrome chromosome region 25), which is highly enriched in KIT- cells and increased expression in aged cells." (PMID 34237055, 2021).
Yersinia infection (1 paper, 2013). "In particular, c-KIT is of great interest as a potential biomarker for susceptibility to Yersinia infection, given our preliminary data showing that primary dendritic cells that express higher c-KIT levels produced less TNF-α in response to Y. pestis infection." (PMID 24206648, 2013). "To determine whether there is a link between c-KIT expression levels and host immune response, we investigated the effect of pathogenic Yersinia infection on pro-inflammatory cytokine production in human dendritic cells expressing naturally varying levels of c-KIT." (PMID 24206648, 2013). "In response to Y. enterocolitica, c-KIT exhibited maximal phosphorylation at ~45 min post-infection in THP-1 cells by Western blot, demonstrating that Yersinia infection is capable of stimulating c-KIT activation, albeit via a delayed response compared to SCF." (PMID 24206648, 2013). "We next investigated c-KIT phosphorylation to assess kinase activation in response to Yersinia infection." (PMID 24206648, 2013).
tumor (1,865 papers, 1993 to 2026). "KRAS and NRAS are genes involved in pathways downstream from KIT, and mutations in these genes promote cell proliferation and tumour development." (PMID 41384700, 2026). "Tyrosine kinase receptors, including KIT (CD117), are a family of receptor proteins that are upregulated in tumor cells, and their mutations are associated with several stromal tumors." (PMID 41596472, 2026). "Multivariate logistic regression determined the association between (i) NRAS and KIT testing and patient/tumour characteristics, and (ii) NRAS genotype and patient/tumour characteristics." (PMID 41378737, 2026). "Despite retaining the original KIT mutation and DOG1 expression, the relapsed tumor lost KIT expression and exhibited a dedifferentiated phenotype." (PMID 41559406, 2026). "Early and accurate identification of specific tumor mutations, such as KIT, PDGFRA, or SDH deficiencies, allows for tailored therapeutic strategies that can significantly improve prognosis and survival rates." (PMID 39927693, 2025). "In the clinical context of GIST, tumour heterogeneity refers to the presence of multiple types of KIT mutations in a patient's tumour tissue." (PMID 39981588, 2025). "We found through single-cell sequencing analysis that the high-risk group was primarily enriched in GRN, TWEAK, and KIT tumor-related signaling pathways." (PMID 41211507, 2025). "The nine other established models (75%) were treated before sampling; three of these tumor samples carried only primary KIT mutations and four had primary and secondary mutations." (PMID 39853155, 2025). "SEs positive for KIT mutations show strong c-KIT activation at the biochemical level, playing a key role in the initiation and especially in tumor progression." (PMID 40723290, 2025). "Imatinib has shown high response rates, particularly in tumors with KIT exon 11 mutations, and is also used in neoadjuvant and adjuvant settings to reduce tumor burden or recurrence risk." (PMID 40964573, 2025). "ctDNA analysis showed good concordance with tissue profiling in patients with higher tumor burden, identifying KIT mutations in 89% and secondary resistance mutations in 55% of cases." (PMID 41355515, 2025). "Although IL-18 signaling typically induces KIT expression to promote tumor growth, A2AR-deficient mature NK cells show reduced IL-18R1 and KIT expression, making them less susceptible to adenosine’s inhibitory effects." (PMID 40297580, 2025). "Four dense cell regions from the same tumor were tested individually, of which only one sample had a KIT exon 17 D820H secondary mutation, indicating an intratumoral heterogeneity." (PMID 40377443, 2025). "There were more tumor samples carrying only a primary KIT mutation, the driving force for GIST tumorigenesis, than tumor samples carrying secondary mutations, mutations appearing after treatment." (PMID 39853155, 2025). "These techniques also enable quantification of the tumor mast cell mass (allelic load) by expressing the allelic fraction of the circulating or medullary KIT D816V mutation, in particularly to monitor possible cytoreductive treatments (cladribine, TKIs)." (PMID 41039576, 2025). "Vatalanib (PTK787/ZK222584) targets several receptors implicated in tumor growth and angiogenesis, including VEGFRs, PDGFRs, and KIT." (PMID 40733131, 2025). "A phase II study of advanced GIST found that 67% of tumours from imatinib‐resistant patients had new or secondary KIT mutations, with exon 11 mutations being the most frequent." (PMID 41230918, 2025). "These tumours are primarily driven (around 80%) by mutations in the c-KIT or PDGFRA genes, leading to the activation of tyrosine kinase pathways that promote tumour growth and survival." (PMID 41426918, 2025).
tumor (continued). "Tumor recurrence after initial imatinib suggests incomplete eradication of minimal residual disease or secondary KIT mutations." (PMID 40823097, 2025). "Four cases had scores below 0.9: Three KIT‐mutated GISTs with a lower tumor percentage had calibrated scores between 0.3 and 0.9, while one SDH‐deficient GIST received no match (calibrated score < 0.3)." (PMID 40145859, 2025). "Screening for the KIT D816V mutation is best performed using ASO-qPCR or digital PCR (technical consensus in Europe) on DNA extracted from skin lesions via an allele amplification technique specific for the KIT D816V mutation." (PMID 41039576, 2025). "Dose-dependent inhibition of KIT autophosphorylation in response to either single or repeated treatment with M4205 was confirmed in other GIST in vivo tumor models bearing different activating and resistance mutations of KIT." (PMID 40018846, 2025). "The KIT mutation-positive subgroup also had a significantly higher rate of tumor recurrence (relative risk [RR]= 2.06, 95% CI: 1.37–3.11; P = 0.0005) and metastasis (RR = 2.77, 95% CI: 1.64–4.67; P = 0.0001) than the KIT mutation-negative subgroup." (PMID 40703587, 2025). "Whereas tumours without any driver-mutation (WT) or with PDGFRA mutations are expected to be imatinib-resistant, tumours with c-KIT mutations are in general imatinib-sensitive." (PMID 41373613, 2025). "Despite being undetectable preoperatively, the tumor was identified by microscopic examination as a spindle cell lesion with a diffuse growth pattern, KIT-positive, and with a C-KIT gene mutation." (PMID 40507589, 2025). "The tumor harbored 2 KIT mutations (p.Y553H and p.Y646C), both of which were confirmed by Sanger sequencing." (PMID 40589558, 2025). "More models were established from donor tumor samples carrying a KIT mutation than from those carrying a PDGFRA mutation, corresponding with the lower incidence and less aggressive behavior of PDGFRA-related disease." (PMID 39853155, 2025). "In one model, however, the patient's donor tumor showed a primary KIT mutation in exon 11 and a secondary mutation in exon 13 (model UZLX-GIST76)." (PMID 39853155, 2025). "In the recurrent tumor, we also detected an additional KIT exon 17 mutation (c.2448C>A; p.Lys818Arg)." (PMID 41355515, 2025). "KIT, a classical proto-oncogene that encodes a receptor tyrosine kinase responsive to stem cell factor, has been found to promote tumor development and progression in various cancers through overexpression or mutations." (PMID 39744132, 2024). "Case reports describing the use of imatinib in the setting of dogs with metastatic MCTs (of either cutaneous or intestinal origin) harbouring KIT mutations have described an initial marked decrease in tumour size." (PMID 38787171, 2024). "Pattern II KIT expression was observed in tumours harbouring KIT mutations, whereas pattern I expression was observed in tumours harbouring wild‐type KIT." (PMID 39177283, 2024). "In this case, a 12‐year‐old male domestic cat with multiple subcutaneous MCTs exhibited marked differences in either the mutation status or expression pattern of KIT/KIT, which was dependent on the tumour location." (PMID 39177283, 2024). "GIST is a highly heterogeneous tumor including various molecular entities with mutually exclusive gain-of-function mutations in KIT or PDGFRA mostly." (PMID 38443340, 2024). "The KIT gene, a tyrosine kinase receptor proto-oncogene, increases cell proliferation, and its mutation gene leads to cellular atypia and neoplasia." (PMID 38993816, 2024). "The pathogenesis of AM involves mechanical stimulation and characteristic tumor-promoting mutations, such as those in the KIT proto-oncogene." (PMID 39408752, 2024). "We report on three generations of a family who underwent panel-based and whole genome sequencing of the tumor and germline and were found to have a gain-of-function variant in exon 13 of the KIT gene, c.1965T>G; p.Asn655Lys (N655K)." (PMID 38538628, 2024).
tumor (continued). "In contrast, GISTs with KIT exon 9 mutations tend to have a higher tumour burden and a poorer prognosis." (PMID 39070147, 2024). "SPRED1 was recently identified as a tumor suppressor in MM and it is often inactivated in the setting of KIT mutation." (PMID 38247727, 2024). "Two RTK inhibitors are currently in use for the treatment of recurrent, non-resectable grade II and III canine MCTs, with the latter requiring confirmation of the presence of KIT mutations in the tumour." (PMID 38787171, 2024). "Polymerase chain reaction (PCR) and histopathological analyses revealed intertumoral heterogeneity among tumour locations based on the mutation status of KIT." (PMID 39177283, 2024). "This case exhibited varying trends in the status of KIT mutations, KIT expression patterns, and responsiveness to therapeutic agents depending on the tumour location." (PMID 39177283, 2024). "Through the WGS of the tumor, a germline variant in KIT, c.1965T>G; p.Asn655Lys (p.N655K) was found." (PMID 38538628, 2024). "KIT mutations have been reported in a wide range of human tumour types, with GOF mutations in exons 8, 9, 11, 12, and 17 being the most common." (PMID 38787171, 2024). "The presence of KIT mutations has been assessed in other canine tumour types, specifically GISTs and oral melanomas." (PMID 38787171, 2024). "It frequently harbors BRAF, NRAS, or KIT mutations which influence both tumor development and treatment strategies." (PMID 37403699, 2023). "Patients harboring KIT exon 13 mutations will receive sunitinib and regorafenib at tumor progression." (PMID 37046997, 2023). "Anlotinib is a multi-target tyrosine kinase inhibitor that can effectively inhibit tumor cell proliferation after receptor kinase activation caused by KIT gene mutation." (PMID 36779523, 2023). "Expression of COMMD3 in luminal-A-like tumours was directly associated with markers of luminal differentiation: c-KIT, ELF5, androgen receptor and tubule formation (the extent of normal glandular architecture; p < 0.05)." (PMID 37072858, 2023). "GIST is a heterogeneous group of tumours that includes a variety of molecular entities with usually mutually exclusive activating oncogene mutations, mostly KIT or PDGFRA mutations." (PMID 36766479, 2023). "Point mutations on KIT can lead to the development of ubiquitinated tumor-specific antigens (TSAs), which are cleaved into epitopes in proteasomes." (PMID 37513844, 2023). "Meanwhile, c‐KIT has also been reported to be deficient in TC cells and involved in tumor differentiation and development." (PMID 37506147, 2023). "In germline analysis, there were no additional findings apart from the 15q11.2-q13 deletion of the paternal allele, while a pathogenic activating KIT mutation was identified in the tumor." (PMID 37575996, 2023). "In epithelioid and mixed variants of GISTs, the expression of KIT/PDGFRA-mutant isoforms is associated with the anatomical site of the tumor." (PMID 37046997, 2023). "This preliminary study suggest that exon 11 mutations in KIT are common in GISTs with intermediate/high recurrence risk especially when the diameter of the tumor is ≥5." (PMID 37901323, 2023). "Conversely, patients with KIT exon 17 mutations will receive regorafenib and sunitinib at tumor progression." (PMID 37046997, 2023). "Jilg and colleagues conducted a prospective clinical trial to assess the presence of tumor-specific c-KIT and PDGFRA mutations in GIST patient plasma." (PMID 37046997, 2023). "Three tumours (14%) had oncogenic PDGFRA exon 18 mutations, and 18 tumours (86%) had KIT exon 11 mutations." (PMID 37622176, 2023).